ISG20 (interferon stimulated exonuclease gene 20)
Diseases named in the same sentence as ISG20 in open-access papers (continued):
Sharing a sentence is not in itself a finding about the gene and the disease.
malaria (1 paper, 2023). Malaria is a serious and sometimes fatal disease caused by a parasite that commonly infects a certain type of mosquito which feeds on humans. "Across B cell subsets, multiple upregulated Type I IFN signaling response genes were detected, including IFNITM2, ISG20, and STAT1, consistent with the important role of Type I IFN signaling in malaria immune responses across multiple cell subsets." (PMID 37968278, 2023).
malignant glioma (1 paper, 2021). A grade III or grade IV glioma arising from the central nervous system. "Previous research has shown that childhood malignant gliomas involve abnormal methylation and silencing of LHX9,108 and the relationship between ISG20, CITED2, and LHX9 with OV and its molecular mechanism must be examined in depth in future studies." (PMID 34609082, 2021).
neuroblastoma (1 paper, 2024). Neuroblastoma (NB) is the most common solid, extracranial childhood tumor. "Six characteristic genes (BATF, CXCR3, GIMAP5, GPR18, ISG20, and IGHM) were identified by machine learning, and these genes are associated with multiple immune-related pathways and immune cells in neuroblastoma." (PMID 39559348, 2024). "BATF, CXCR3, GIMAP5, GPR18, ISG20, and IGHM may serve as biomarkers that reflect the conditions of the immune microenvironment of neuroblastoma and hold promise in guiding neuroblastoma treatment." (PMID 39559348, 2024).
ovarian tumor (1 paper, 2021). "The expression levels of ANGPTL4, PYGB and IRS2 were upregulated and those of ISG20 and SEH1L were downregulated in ovarian tumor tissues compared with normal tissues." (PMID 34229669, 2021).
parasitemia (1 paper, 2016). "C57BL/6 mice infected with N67 parasite induced a strong IFN-I response, including increased expression of genes such as Cd40, Isg15, Isg20, Ifit2, Mx1, Mx2, Ddx58, and Usp18 genes, leading to suppression of N67 parasitemia." (PMID 27716849, 2016).
periodontitis (1 paper, 2021). An acute or chronic inflammatory process that affects the tissues that surround and support the teeth. "The strong associations among ISG20, ESRP1 and activated B cell, BCR signaling pathway, and HLA-DOB in periodontitis were first identified in our study." (PMID 34285922, 2021). "The most positively correlated immunocyte-RBP pair is activated B cell and ISG20, both significantly upregulated in periodontitis." (PMID 34285922, 2021). "Correlation analysis demonstrated that the most positively correlated immune pathway-RBP pair is BCR signaling pathway (B cell receptor signaling pathway) and ISG20, with higher activities of both in periodontitis." (PMID 34285922, 2021). "Our study depicted the correlations among RBPs and immune microenvironment and biological reactions in periodontitis, with strong correlations of the RBPs ISG20 and ESRP1 with activated B cell infiltration, BCR signaling activation, and HLA-DOB expression." (PMID 34285922, 2021). "Correlation analysis revealed HLA-DOB and ISG20 as the most positively correlated HLA-RBP pair, with higher activities of both in periodontitis." (PMID 34285922, 2021). "ISG20 and ESRP1 were found to be highly correlated with immunocyte infiltration, immune signaling activation, and HLA expressions in periodontitis." (PMID 34285922, 2021). "Paired with the immune characteristics above, the most strongly correlated RBPs were ISG20 and ESRP1, suggesting that ISG20 and ESRP1 might have potent impact on the immune microenvironment in periodontitis." (PMID 34285922, 2021).
prostate tumors (1 paper, 2013). "This analysis revealed a prominent inverse correlation between uc.106 + A expression and the expression of many interferon pathway genes such as IRF7, ISG15, ISG20, OAS1-3, and PTPN22 in prostate tumors." (PMID 23409773, 2013).
testis tumors (1 paper, 2023). "The results showed that ISG20 was uniformly overexpressed in brain, uterus, breast, cervix, esophagus, kidney, liver, pancreas, skin, and testis tumors across the GENT2 and TCGA databases." (PMID 37380984, 2023).
thyroid tumor (1 paper, 2023). A benign or malignant neoplasm affecting the thyroid gland. "In contrast, decreased expression of ISG20 was observed in the blood, bone, colon, endometrium, prostate, stomach, and thyroid tumors." (PMID 37380984, 2023).
Ureteral obstruction (1 paper, 2025). Obstruction of the flow of urine through the ureter. "Using the unilateral ureteral obstruction (UUO)-induced renal fibrosis mouse model, we confirmed elevated Isg20 expression, promoted renal fibrosis, and increased ribosome biogenesis." (PMID 40622935, 2025).
vulvar tumors (1 paper, 2023). "ISG20 expression was lower in normal tissues than in neoplastic sites across the majority of cancer types, including adrenal gland, brain, breast, cervix, esophagus, kidney, liver, lung, oral, ovary, pancreas, skin, testis, tongue, uterus, and vulvar tumors." (PMID 37380984, 2023).
infection (58 papers, 2008 to 2026). The state of being infected such as from the introduction of a foreign agent such as serum, vaccine, antigenic substance or organism. "No significant loss of cell viability was observed in Wild-type, ISG20-KO, or ISG20-OE cells at 72 h post-infection compared to mock-infected controls." (PMID 41304224, 2025). "As expected, peritoneal macrophages (PEM) isolated from isg20-/- mice exhibited an increased susceptibility to infection (in both percentage of infected cells as well as in their MFI), thus confirming a primary role for ISG20 in intracellular innate defenses." (PMID 31600344, 2019). "Additionally, Isg20−/− mice experienced more-rapid weight loss than WT mice after VEEV-G3A infection." (PMID 30232164, 2018). "However, in vivo, the increased susceptibility of Isg20−/− mice to VEEV-G3A infection may also be due to interferon induction differences, which may or may not be related to differences in upregulation of the specific ISGs identified in our in vitro screens." (PMID 30232164, 2018). "In Western blot kinetics, we observed that inhibition of HCMV replication by ISG20 occurs at the early stage of infection which correlated with reduced amounts of viral early and late transcripts." (PMID 41511982, 2026). "Western blot analysis of HCMV-infected cells revealed an upregulation of ISG20 early during infection, followed by a decrease in ISG20 protein levels, which appeared to be more pronounced in cells infected with HCMV strain TB40/E compared to AD169." (PMID 41511982, 2026). "ISG20 exerts 3′-5′ exonuclease activity against different viruses, including flaviviruses, and it was rapidly induced in trophoblast cells after infection with ZIKV." (PMID 39940721, 2025). "Infection induced a significant upregulation of pulmonary interferon-stimulated genes (ISGs), such as Mx1 and Isg20 (indicators of viral replication), as early as 2 dpi in both young and aged mice." (PMID 41145556, 2025). "We observed that ISG20 expression is dynamically regulated during BKPyV infection: it is upregulated both during early infection and by expression of the viral large T antigen (LT) alone." (PMID 41304224, 2025). "Despite observing robust ISG downregulation in infected cells 12 h post-infection, ISG20 remains expressed in RSV-infected cells." (PMID 40815167, 2025). "In contrast, the expression of SPOCK2 and ISG20 was upregulated following infection with both bovine- and mink-derived H5N1." (PMID 41157297, 2025). "We previously established a BKPyV infection system in TCCSUP cells, a urothelial-derived line that is relevant to the primary site of BKPyV replication, and observed that infection induced endogenous ISG20 expression." (PMID 41304224, 2025). "VP1 levels increased progressively after infection, whereas both LT and ISG20 exhibited an initial upregulation (reaching a peak at day 3) followed by a decline." (PMID 41304224, 2025). "When overexpressed in vitro, ISG20 restricted infections by EMCV, vesicular stomatitis virus, influenza virus, HIV and Sindbis virus, WNV, and HCV (39, –, 42)." (PMID 40638072, 2025). "ISG20 and Ifit2 also followed a similar pattern of expression where their levels were up-regulated upon infection but treatment with the inhibitor, BX795 resulted in a reduction in their levels." (PMID 39509467, 2024). "We also noticed that IRF7 and ISG20 expression fell slightly below baseline near 28 days postsymptom-onset, suggesting potential downregulation of these genes at later stages of infection." (PMID 38580667, 2024). "Our results demonstrate that while mRNA levels of Ceacam1 remained unchanged among groups, those mice supplemented with vitamin D exhibited elevated expression of Ifnb1, Isg15, and Isg20 following MHV-3 infection." (PMID 38140675, 2023). "Our findings showed that vitamin D supplementation prior MHV-3 infection enhanced the expression of IFN-β and the interferon-stimulated genes Isg15 and Isg20 in the lungs upon infection." (PMID 38140675, 2023).
infection (continued). "ISG20 expression has been shown to be elevated in the course of infection and a potential biomarker for several types of cancer." (PMID 34630514, 2021). "Transcripts of Ifnb (A) or ISGs (Cxcl10, Isg20, Ccl5, Isg15) (B) were determined 6 hr after infection." (PMID 32886065, 2020). "Transcripts of Ifnb (B) or ISGs (Cxcl10, Isg20, Ccl5, Isg15) (C) were determined at 6 hr after infection." (PMID 32886065, 2020). "When MEFs were primed with 10 and 100 IU of IFN-α4/β at a 1:1 ratio for 4 h, we observed similar differences in virus replication, with ∼10-fold-greater infection in Isg20−/−MEFs than in B6 MEFs." (PMID 30232164, 2018). "The VLP system we used can complete only a single round of infection yet was potently inhibited by ISG20." (PMID 29695422, 2018). "Using this approach, all three S-segment RNAs appeared to be diminished substantially (∼10-fold) by ISG20 following infection of Vero cells." (PMID 29695422, 2018). "VEEV-G3A was more sensitive to the antiviral effects of ISG20, as infection was restricted completely at 6 and 12 h.p.i." (PMID 30232164, 2018). "Studies have shown that ISG20 inhibits HBV replication via degrading HBV-RNA molecules during infection." (PMID 29963243, 2018). "Crucially, the highly specific antibunyaviral activity of ISG20 was also evident in these bulk populations, as parallel infections with single-cycle RVFV (strain 35/74) were completely unaffected by ISG20." (PMID 29695422, 2018). "VEEV-G3A infection in the draining popliteal lymph node (PLN) was elevated in Isg20−/− mice compared to B6 mice at 12 h.p.i." (PMID 30232164, 2018). "Ectopic expression of ISG20 in MEFs reduced infection of WT CHIKV and VEEV by approximately 100-fold at 12 and 24 h postinfection (h.p.i.)." (PMID 30232164, 2018). "Studies performed with hepatitis B virus (HBV) suggested that ISG20 restricts viral replication by directly degrading viral RNAs and genomic intermediates produced over the course of infection." (PMID 30232164, 2018). "The basal and cytokine-inducible expression of intrahepatic ISG20 indicates a potentially important role of ISG20 in host defense mechanisms against pathogen infections in hepatocytes." (PMID 28399146, 2017). "Consistently, deletion of FBXW7 in macrophages also led to decreased expression of ISG15 and ISG20 mRNAs after infection with VSV, H1N1 virus or RSV." (PMID 28287082, 2017). "In the DOCK5-ko cells, the expression of ISG20 increased to over 20-fold 2 days after post-infection." (PMID 29214055, 2017). "Next, we assessed the antiviral function of ISG20 in an HBV in vitro infection system, specifically, the viral receptor NTCP reconstituted HepG2 cells." (PMID 28399146, 2017). "We found that infection with the IFN-sensitive RRV strain resulted in the robust induction of several well-defined ISGs, including those encoding IFIT1/2/3, ISG15, ISG20, RSAD2, and Mx2." (PMID 27128797, 2016). "However, our data also demonstrate a significant downregulation of ISG20 during prolonged BKPyV infection, potentially reflecting a viral evasion strategy, as continuous high expression of ISG20 can be harmful to cell survival." (PMID 41304224, 2025). "The synchronous dynamic expression of LT and ISG20 during infection may reflect an evolutionary balance: early LT-mediated ISG20 induction could prevent excessive viral spread, while later-phase decline may facilitate viral persistence." (PMID 41304224, 2025). "Noteworthy, two ISGs were further upregulated 24 h post-infection in M1-MDMs: ISG20 and OAS2." (PMID 39940721, 2025). "However, endogenous ISG20 expression becomes significantly suppressed during later stages of infection, coinciding with declining LT levels." (PMID 41304224, 2025). "Infection of microglia was associated with a sharp increase in CCL2 and CXCL10 chemokine gene expression and the activation of many type I interferon stimulated genes (MX1, ISG15, ISG20, IFI27, IFITM3 and others)." (PMID 38737767, 2024).
infection (continued). "We investigated whether HBV infection of Wt or Samhd1 KO cells induced the expression of APOBECs along with MxA and ISG20 following a 6-h synchronized infection." (PMID 30918010, 2019). "ISG20 has been shown to restrict infection of multiple RNA and DNA viruses (3, 13, –, 20)." (PMID 30232164, 2018). "Thus, it is likely that following VLP infection, ISG20 directly targeted the L, M, and S minigenome segments." (PMID 29695422, 2018). "CHIKV or VEEV expressing GFP as a nonstructural protein 3 (nsP3) fusion was used to determine whether ISG20-dependent restriction was a result of fewer cells initiating infection or represented a uniform reduction in replication efficiency." (PMID 30232164, 2018). "ISG20 was up-regulated by over 8-fold 2 days post-infection." (PMID 29214055, 2017). "Cells with overexpressed ISG20 are resistant to the infections of RNA viruses including vesicular stomatitis virus (VSV), influenza virus, encephalomyocarditis virus (EMCV), hepatitis A and C virus (HAV and HCV), yellow fever virus, and HIV, but not to a DNA virus, adenovirus." (PMID 28399146, 2017). "Furthermore, a clear delay in the replication of various strains of human cytomegalovirus and of herpes simplex virus type I was detected by multistep growth curve analyses after infection of primary human fibroblasts with doxycycline-inducible expression of ISG20." (PMID 41511982, 2026). "In addition, the ISG20 gene was also upregulated in NPCs 48 h post-infection." (PMID 36142200, 2022). "The observed differences in viral replication suggest that ISG20 may participate in orchestrating innate immune responses in particular cell types, which affects the outcome of infection with IFIT1-sensitive viruses, which are less able to evade host antiviral responses." (PMID 30232164, 2018). "In fact, infection with an IE1-deleted HCMV induced a stronger and more permanent increase of ISG20 expression." (PMID 41511982, 2026). "Consistent with the notion, that the ISG20-induced gene signature consisting of upregulated ISGs, ZNFs and TEs augments the IFN-mediated host cell defense we observed that ISG20 enhanced both IFN-beta and ISG expression after infection with HCMV." (PMID 41511982, 2026). "Ovine cells reacted with especially strong upregulation of Isg15, Isg20, and Ifnb-2 after BATV, lNRIV, or BAYAV infection." (PMID 39772143, 2024). "The upregulation of ISG15, ISG20, ISG15 family ligases (HERC5/6), and ISG15 proteases (USP18) also appeared upon infection, which has been reported to participate in host antiviral immunity." (PMID 37752509, 2023). "BeAn-infected SJL mice express several genes involved in the innate immune responses (Tlr7, Tlr8, Tlr9, Myd88, Isg15, Isg20, Mx1, and IL6) in the spinal cord during the late phase of TMEV-IDD at 165 days post infection." (PMID 30669615, 2019). "More-dramatic differences were observed with VEEV-G3A, as Isg20−/− MEFs exhibited a 100-fold to 10,000-fold increase in VEEV-G3A infection compared to WT MEFs (P < 0.01)." (PMID 30232164, 2018). "By 24 h.p.i., all WT mice had evidence of infection in their PLN, a time point at which time viremia was elevated ∼2-fold in Isg20−/− mice (P < 0.05)." (PMID 30232164, 2018). "Induced tet-off MEFs expressing ISG20, ExoII, or control GFP were infected with CHIKV (multiplicity of infection [MOI] of 5) and treated with cycloheximide." (PMID 30232164, 2018). "Infection of primary monocytes with PDK53 at both 1 and 10 MOI resulted in greater levels of CXCL10, ISG20 and IFIT2 mRNA levels compared to 10 MOI of 16681." (PMID 27185466, 2016). "In general, DCs were more responsive than Mφs to infection, with more genes induced, such as SOCS2, ISG20, TRAF5 and IRF4." (PMID 18167562, 2008). "HFF/ISG20, HFF/ISG20mut and control cells were infected with HCMV (strain AD169, MOI of 1) and harvested for RNA isolation at 48 hpi, since the antiviral activity of ISG20 was observed from early times after infection." (PMID 41511982, 2026).